KLF8 (KLF transcription factor 8)
Diseases named in the same sentence as KLF8 in open-access papers (continued):
Sharing a sentence is not in itself a finding about the gene and the disease.
bladder cancer (5 papers, 2019 to 2023). "The knockdown of NEDD4 significantly suppressed the K63-linked poly-ubiquitination of KLF8 in bladder cancer cells." (PMID 37568787, 2023). "NEDD4 and KLF8 were overexpressed in bladder cancer tissues and were associated with poorer patient survival rates." (PMID 35031788, 2022). "The experimental data revealed that NEDD4 and KLF8 were overexpressed in bladder cancer tissues and cells and were associated with poor patient survival rates." (PMID 35031788, 2022). "In this study, we investigated the underlying molecular mechanism by which the NEDD4-mediated KLF8/miR-132/NRF2 axis fine-tunes the malignant phenotypes of bladder cancer cells using in vitro and in vivo assays, providing a promising therapeutic target for treating patients with bladder cancer." (PMID 35031788, 2022). "In bladder cancer, NEDD4 depletion significantly downregulated endogenous KLF8 ubiquitination, which affected the K63-linked polyubiquitination of KLF8, while K48-linked polyubiquitination remained unchanged." (PMID 37497216, 2023). "Collectively, these findings provide evidence that NEDD4 promotes bladder cancer progression by increasing the levels of KLF8 and NRF2." (PMID 37568787, 2023). "Next, we cotransfected Flag-NEDD4, Myc-KLF8, and HA-Ub plasmids into T24 bladder cancer cells, and Myc was adopted for the IP assay to examine the ubiquitination of KLF8." (PMID 35031788, 2022). "They found that NEDD4 was highly expressed in bladder cancer cells, and that it stabilised and promoted the activity of a transcription factor, Kruppel-like factor 8 (KLF8)." (PMID 35031788, 2022). "Meanwhile, the correlation between the expression of NEDD4 and KLF8 in tumor tissues and clinicopathological parameters in bladder cancer was analyzed." (PMID 35031788, 2022). "Our results suggest that NEDD4 augments the viability and invasive ability of bladder cancer by regulating the KLF8/miR-132/NRF2 axis." (PMID 35031788, 2022). "The coexpression relationship between NEDD4 and KLF8 in bladder cancer was identified through the biological website Chipbase v2.0." (PMID 35031788, 2022). "In the current study, we revealed that KLF8 promotes the viability and migratory ability of bladder cancer cells by inhibiting expression of miR-132." (PMID 35031788, 2022). "KLF8 inhibited the expression of miR-132 to augment the viability and migratory ability of bladder cancer cells." (PMID 35031788, 2022). "Our experimental data suggested that NEDD4 intensified the stability and transcriptional activity of KLF8 through ubiquitination to augment the viability and migratory ability of bladder cancer cells." (PMID 35031788, 2022). "The 5-year overall survival analysis revealed that increased expression of NEDD4 and KLF8 was closely related to poorer survival rates of patients with bladder cancer." (PMID 35031788, 2022). "Furthermore, oncogenesis was induced in bladder cancer when the expression of KLF8 was stabilized from proteasome-mediated degradation by ELF3-AS1 in bladder cancer." (PMID 35031788, 2022). "Hence, in this study, we intended to characterize the functional relevance of the NEDD4-mediated Kruppel-like factor 8/microRNA-132/nuclear factor E2-related factor 2 (KLF8/miR-132/NRF2) axis in the development of bladder cancer." (PMID 35031788, 2022). "Moreover, we predicted the coexpression relationship between NEDD4 and KLF8 in bladder cancer via in silico analysis, which was validated in clinical samples." (PMID 35031788, 2022). "Subsequently, we investigated whether KLF8 facilitates the viability and migratory ability of bladder cancer cells by regulating the expression of miR-132." (PMID 35031788, 2022). "Moreover, miR-132 is downregulated by KLF8, which is overexpressed in bladder cancer." (PMID 37497216, 2023).
bladder cancer (continued). "In addition, the expression of NEDD4 and KLF8 was elevated in bladder cancer cell lines (EJ-m3, T24, J82, BIU-87, and SW780) compared to that of the normal urothelial cell line SVHUC-1, with the highest expression in T24 cells, which were therefore selected for subsequent experiments." (PMID 35031788, 2022). "Furthermore, we sought to examine whether NEDD4 regulates the viability and migratory ability of bladder cancer cells through KLF8." (PMID 35031788, 2022). "KLF8 acts as a transcription factor in the Sp/KLF family and stimulates and promotes migration of bladder cancer cells." (PMID 37497216, 2023). "In bladder cancer cells, NEDD4 intensified the stability and transcriptional activity of KLF8 through ubiquitination to augment cell viability and migratory ability." (PMID 35031788, 2022). "In bladder cancer cells, NEDD4 stabilizes the expression of KLF8 and promotes the transcriptional activity of KLF8 by promoting the ubiquitination of KLF8." (PMID 35031788, 2022). "The tumor tissues and adjacent normal tissues of 45 patients with bladder cancer were resected and obtained, and RT-qPCR and western blot assays were adopted to verify the expression levels of NEDD4 and KLF8." (PMID 35031788, 2022). "Moreover, KLF8 is a transcription factor in the Sp/KLF family and has a pivotal role in cancer metastasis by stimulating the proliferation and migratory ability of bladder cancer cells." (PMID 35031788, 2022). "Therefore, this study aimed to delineate new mechanisms by which the NEDD4-mediated KLF8/miR-132/NRF2 axis exerts its oncogenic effects in the initiation and development of bladder cancer." (PMID 35031788, 2022). "The expression of NEDD4 and KLF8 in highly differentiated bladder cancer tissue (G1) was lower than that in moderately differentiated bladder cancer tissue (G2), while in poorly differentiated bladder cancer tissue (G3), NEDD4 and KLF8 exhibited the highest expression levels." (PMID 35031788, 2022).
lung carcinoma (4 papers, 2019 to 2024). "Of importance, KLF8 has been implicated to be regulated by miRNAs in metastatic progression of lung cancer." (PMID 32411796, 2020). "Further gain-of-function and loss-of-function experiments demonstrated that KLF8 facilitated the growth of lung cancer cells A549 and H1299." (PMID 31624471, 2019). "KLF8 has been proved to be regulated by miR-1236-3p and miR-135a in metastatic progression of lung cancer." (PMID 32411796, 2020). "Our evidence demonstrated that KLF8 upregulation in human lung cancer promotes the cell proliferation and colony formation of lung cancer cells." (PMID 31624471, 2019). "The phenotypic results showed that KLF8 knockdown decreased the proliferation rate and colony formation of lung cancer cells." (PMID 31624471, 2019). "In the present work, we provided evidence that the transcriptional factor KLF8 functions as a favorable factor for the growth of human lung cancer cells." (PMID 31624471, 2019). "To explore the effects of KLF8 high expression on lung cancer cells, we generated A549 cells with KLF8 stable overexpression by infecting the cells with lentivirus-mediated overexpression of KLF8 and selecting with puromycin." (PMID 31624471, 2019). "KLF8 was knocked down with lentivirus-mediated short-hairpin RNA (shRNA) in human lung cancer cells (A549 and H1299 cells)." (PMID 31624471, 2019). "We observed that the expression levels of KLF8 were overexpressed in human lung cancer tissues and KLF8 facilitated the proliferation and colony formation of human lung cancer cells." (PMID 31624471, 2019). "We next prepared A549 and H1299 cells with stable KLF8 knockdown and those cells were subjected to analyze the effects of KLF8 on lung cancer cell growth." (PMID 31624471, 2019). "Taken together, these findings showed that JMJD2A contributed to the function of KLF8 in human lung cancer cells." (PMID 31624471, 2019). "Taken together, these findings demonstrated that KLF8 regulated the cell cycle of lung cancer cells." (PMID 31624471, 2019). "By utilizing lentivirus-mediated knockdown and overexpression of KLF8, we demonstrated that KLF8 promoted the growth (proliferation and colony formation) of lung cancer cells A549 and H1299." (PMID 31624471, 2019). "Here in the present report, we demonstrate that KLF8 overexpression in human lung cancer promotes cell cycle progress via a JMJD2A-dependent manner." (PMID 31624471, 2019). "qRT-PCR and western blot analysis demonstrated that KLF8 was significantly knocked down by lentivirus-mediated shRNA in these two lung cancer cell lines." (PMID 31624471, 2019). "We first analyzed the effects of KLF8 on cell survival of lung cancer cells since apoptosis-resistance is a key feature of lung cancer cells." (PMID 31624471, 2019). "To investigate the function of KLF8 in human lung cancer, we first tested the expression of KLF8 in human lung cancer tissues." (PMID 31624471, 2019). "We observed that the expression level of KLF8 was remarkedly upregulated in human lung cancer tissues." (PMID 31624471, 2019). "When our manuscript was under preparation, another two reports also reported that KLF8 mRNA and protein levels were overexpression in human lung cancer tissues and the high expression of KLF8 was significantly correlated with TNM stage, lymph node metastasis and poor overall survive." (PMID 31624471, 2019). "In addition, KLF8 was highly expressed in human lung cancer cells lines compared with normal lung epithelial cells, and A549 and H1299 expressed the highest levels of KLF8 among the tested lung cancer cell lines." (PMID 31624471, 2019). "We next explored the mechanism by which KLF8 contributes to the hyper-growth of lung cancer cells." (PMID 31624471, 2019). "Indeed, we observed KLF8 regulated the expression of CDK4 and P21 depending upon JMJD2A, which also contributed to the functions of KLF8 in regulating cell cycle and growth of lung cancer cells." (PMID 31624471, 2019).
lung carcinoma (continued). "miR-1236-3p and miR-135a could inhibit the metastatic procedure of lung cancer by targeting KLF8." (PMID 32411796, 2020). "Therefore, KLF8 may serve as a potential prognostic factor for predicting the progress and outcome of patients with lung cancer." (PMID 31624471, 2019). "KLF8 may serve as a target for the treatment of human lung cancer." (PMID 31624471, 2019). "We investigated whether JMJD2A was involved in the function of KLF8 in lung cancer cells." (PMID 31624471, 2019). "Therefore, it is interesting to explore whether KLF8 regulates the transformation and metastasis of lung cancer cells in further work." (PMID 31624471, 2019). "Among the KLFs, the clear promoting effects on lung cancer were KLF5, KLF7, KLF8, and KLF15, as well as KLF4 and KLF6, which have dual functions." (PMID 38560274, 2024). "In this paper, KLFs have been summarized via systematic reviews, with either a promoting (KLF4 ∼ KLF8, KLF15) or an inhibiting (KLF2 ∼ KLF6, KLK9 ∼ KLF12 and KLF17) roles, which should be useful to monitor lung cancer progression or understand its mechanisms." (PMID 38560274, 2024). "However, the roles of KLF8 in human lung cancer remain largely unknown." (PMID 31624471, 2019). "Thus KLF8 may serve as a potential target for the treatment of human lung cancer." (PMID 31624471, 2019). "However, the roles of KLF8 in human lung cancer remains unknown." (PMID 31624471, 2019). "Here we observed that the expression levels of KLF8 were significantly overexpressed in human lung cancer tissues compared with non-cancer tissues." (PMID 31624471, 2019). "The results showed that the mRNA and protein levels of KLF8 were significantly increased in human lung cancer tissues compared with adjacent non-cancer tissues." (PMID 31624471, 2019). "To this end, we collected fresh lung cancer tissues (n = 34) and adjacent non-cancer tissues (n = 16), and then we analyzed the mRNA and protein levels of KLF8 with qRT-PCR and western blot respectively." (PMID 31624471, 2019). "KLF8 regulated the cell cycle but not apoptosis of lung cancer cells depending upon the histone demethylase JMJD2A." (PMID 31624471, 2019). "KLF8 regulated the expression of the cell cycle regulators P21 and CDK4 in a JMJD2A-dependent manner and JMJD2A knockdown significantly blocked the functions of KLF8 in regulating cell cycle and proliferation of lung cancer cells." (PMID 31624471, 2019). "KLF8 regulated the cell cycle but not survival of lung cancer cells depending on its regulation of the expression of the histone demethylase JMJD2A." (PMID 31624471, 2019). "Next, we showed that KLF8 regulated cell cycle at the G0 phase but not regulates cellular apoptosis of lung cancer cells." (PMID 31624471, 2019). "By contrast, lentivirus-mediated KLF8 overexpression promoted the growth of lung cancer cells (A549 and H1299 cells) and non-cancerous bronchial epithelial cell line BEAS-2B." (PMID 31624471, 2019). "Our further immunohistochemical staining assay also confirmed that KLF8 expression was overexpressed in lung cancer tissues compared with non-cancer tissues." (PMID 31624471, 2019). "The promoting effect of KLF8 on cell proliferation was also observed in H1299 lung cancer cells and BEAS-2B non-cancerous bronchial epithelial cells." (PMID 31624471, 2019). "We also found that KLF8 regulated the cell cycle but not survival of lung cancer cells." (PMID 31624471, 2019). "Therefore, KLF8 controlled cell cycle but not survival of lung cancer cells." (PMID 31624471, 2019).
renal cell carcinoma (4 papers, 2012 to 2023). "KLF8 protein and mRNA expression was not only significantly higher in renal cell carcinoma (RCC) than in non-neoplastic renal tissue, inhibition of KLF8 via siRNA could also induce cell apoptosis in vitro and reduced tumor growth in vivo." (PMID 22276196, 2012).
brain tumors (2 papers, 2012 to 2023). "This study was performed in order to assess for the first time expression and functional impact of KLF8, a member of the Krüppel-like transcription factor family, in primary brain tumors." (PMID 22276196, 2012). "KLF6 expression is elevated in ovarian malignancies, KLF8 promotes cellular proliferation in HCC, gastric, and glioma carcinomas, while KLF3 and KLF14 have been reported to inhibit tumor growth in breast and brain tumors, respectively." (PMID 37833790, 2023).
breast tumor (2 papers, 2016 to 2023). "To test this idea, we overexpressed or reduced KLF8 expression in MDA-MB-231 and SUM159 cells and assessed mRNA and protein expression of major stem cell factors that are associated with breast tumor development and include OCT4, SOX2, NANOG and c-MYC." (PMID 37152043, 2023). "To test whether KLF8 is required for breast tumor growth, we injected luciferase expressing SUM159 cells stably expressing control or KLF8 shRNA into the mammary fat pad of immunodeficient mice." (PMID 37152043, 2023).
colon cancer (2 papers, 2019 to 2023). "We generated CRISPR/Cas9‐mediated knockout (KO) of negative control (NC) and Klf12 in mouse colon cancer CT26 cells, and we also generated KO of Klf8 as a control." (PMID 37606530, 2023).
colorectal cancer (2 papers, 2015 to 2016). A primary or metastatic malignant neoplasm that affects the colon or rectum. "Taken together, this work identified KLF8-induced FHL2 activation as a novel and critical signaling mechanism underlying human breast/colorectal cancer invasion and metastasis." (PMID 26320172, 2015). "Furthermore, recent studies indicate that KLF8 mediates a number of oncogenic processes including transformation and metastasis in ovarian, breast, bladder, and colorectal cancers." (PMID 27534536, 2016).
glioblastoma (2 papers, 2011 to 2012). The most malignant astrocytic tumor (WHO grade IV). "FAK can promote cell cycle progression through activation of ERK and induction of the transcription factor Kruppel-like factor 8 (KLF8), which activates transcription of cyclin D1, as well as through inhibition of p27(Kip1) expression in glioblastoma cells." (PMID 21602932, 2011).
liver cancer (2 papers, 2013 to 2018). An epithelial or non-epithelial malignant neoplasm that arises from the liver. "Some studies have reported that abnormal gene expression, such as that of CD151, CD44, CD44s, CK-19, MMP, OPN, KLF8, TGF-beta and HRP-3, is closely associated with the development and progression of liver cancer." (PMID 24324629, 2013). "The mRNA levels of KLF8 and VEGFA in the same liver cancer samples were detected by qPCR, and the relative Ct values for KLF8 and VEGFA were 8.29 ± 2.01 and 4.63 ± 1.32, respectively." (PMID 30479372, 2018).
lymph node metastasis (2 papers, 2019 to 2022). "High expression of KLF8 was correlated with TNM stage, lymph node metastasis and poor overall survive." (PMID 31624471, 2019). "Results revealed a significant correlation between the expression of NEDD4 and KLF8 and clinical-grade and lymph node metastasis, yet neither patient age nor sex was correlated with the expression of NEDD4 and KLF8." (PMID 35031788, 2022).
non-small cell lung carcinoma (2 papers, 2019 to 2024). A group of at least three distinct histological types of lung cancer, including non-small cell squamous cell carcinoma, adenocarcinoma, and large cell carcinoma. "Inhibition of circ_0067934 could block metastasis, proliferation, and epithelial-mesenchymal transition (EMT) in non-small cell lung cancer (NSCLC) cells via miR-1182/KLF8 axis." (PMID 37608665, 2024). "However, the roles of KLF8 in human non-small cell lung cancer remain unknown." (PMID 31624471, 2019). "The mRNA and protein levels of KLF8 in human non-small cell lung cancer tissues were overexpressed compared with the non-cancer tissues." (PMID 31624471, 2019).
renal carcinoma (2 papers, 2013 to 2023). A carcinoma arising from the epithelium of the renal parenchyma or the renal pelvis. "siRNA knockdown of KLF8 limited cellular growth and invasion capacity of human renal carcinoma cells in vitro." (PMID 37580336, 2023). "Therefore, KLF8 likely plays a role in proliferation of renal carcinoma cells." (PMID 37580336, 2023).
triple-negative breast carcinoma (2 papers, 2023 to 2025). An invasive breast carcinoma which is negative for expression of estrogen receptor (ER), progesterone receptor (PR), and human epidermal growth factor receptor 2 (HER2). "Together, these data suggested that KLF8 regulates RNA and protein levels of the pluripotency transcription factors in triple negative breast cancer cells." (PMID 37152043, 2023). "Together, these data suggest that in triple negative breast cancer cells, KLF8 expression is necessary and sufficient to promote CSCs-phenotypes in vitro." (PMID 37152043, 2023). "Importantly, overexpression of KLF8 induced resistance against paclitaxel in vitro suggesting a potential role of KLF8 in regulating chemoresistance in triple negative breast cancer cells." (PMID 37152043, 2023). "Together, these data confirm the role of KLF8 and the KLF8/OGT loop in promoting stemness and chemoresistance of triple negative breast cancer cell, which may be used to develop strategy in BCSCs-specific treatment." (PMID 37152043, 2023).
brain cancer (1 paper, 2021). A primary or metastatic malignant neoplasm affecting the brain. "Further investigation into the role of Klf8 in the efficacy of antidepressants may help introduce a new class of treatment for brain cancers— an attractive option for drugs that are already on the market and can cross the blood brain barrier." (PMID 34211495, 2021). "Furthermore, because antidepressants seem to inactivate Klf8, it is possible that antidepressants may help treat brain cancers." (PMID 34211495, 2021).
developmental delay (1 paper, 2016). "While the exact role(s) of KLF8 during early embryogenesis has not been examined in detail, a hemizygous gene-trapped KLF8 allele exhibits developmental delay at mid-gestation; although with variable penetrance in the gene-trapped embryos examined." (PMID 27534536, 2016).